ENSG00000259171 (novel protein, ANG-RNASE4 readthrough)
Gene: Protein-coding gene on chromosome 14 (20,684,587 to 20,700,576, forward strand). Ensembl gene ENSG00000259171.
Genetic constraint (gnomAD): Loss-of-function variants: 2 observed, 2.99 expected, observed/expected ratio (o/e) 0.67, 90% interval 0.26 to 1.74. That is too few expected variants to judge how well the gene tolerates losing a copy. Missense variants: 35 observed, 39.88 expected, observed/expected ratio (o/e) 0.88, 90% interval 0.67 to 1.16. Synonymous variants: 16 observed, 19.72 expected, observed/expected ratio (o/e) 0.81, 90% interval 0.55 to 1.23.